EXO1 (exonuclease 1)
Diseases named in the same sentence as EXO1 in open-access papers (continued):
Sharing a sentence is not in itself a finding about the gene and the disease.
tumor (continued). "First, we investigated EXO1 expression in tumor and non-tumor liver tissues in three different clinical studies from the Oncomine database." (PMID 32626539, 2020). "The results showed that the expression of EXO1 was significantly higher in tumor tissues than that in their adjacent non-tumor tissues." (PMID 32626539, 2020). "The overlap with differentially expressed genes in tumor versus normal breast tissues identified a subset of 24 genes, 4 of which associated to the highest negative prognostic impact in BC (KHDRBS1, EXO1, CHEK1, BARD1)." (PMID 35217791, 2022). "Finally, the five candidate genes DNMT3B, EXO1, MCM10, CENPF and CENPE were combined in a new prognosis tool, Gene Expression Classifier or GEC, that stratifies patients according to the number of activated genes in the corresponding tumour (activation status ON)." (PMID 37592220, 2023).
infection (8 papers, 2013 to 2025). The state of being infected such as from the introduction of a foreign agent such as serum, vaccine, antigenic substance or organism. "It is also possible that Vpr depletes Exo1 in producer cells to prevent Exo1 incorporation into the HIV-1 virion for restricting the infection in the target cell." (PMID 30352932, 2018). "The results of our spreading infection assays in Exo1-depleted CEM.SS T cells clearly show that Exo1 inhibits HIV-1 replication." (PMID 30352932, 2018). "Exo1 is a major intracellular immunoreactive protein that can trigger host immune responses during infection." (PMID 26263509, 2015). "Hence, they could partner with Exo1, each processing a distinct set of HIV-1 replication intermediates, to restrict infection." (PMID 30352932, 2018).
gastrointestinal tract cancer (1 paper, 2020). "It seems that MSH6 and EXO1 genetic mutations play an important role in gastrointestinal tract cancer with the EMAST+/MSI-H phenotype." (PMID 32120855, 2020).
head and neck tumors (1 paper, 2020). "The p.E589K mutation in EXO1 has been reported to affect the response to cisplatin treatment in patients with head and neck tumors, and thus may also be functional." (PMID 32300177, 2020).
intestinal disorder (1 paper, 2024). A non-neoplastic or neoplastic disorder that affects the small or large intestine. "For instance, Faecalibacterium prausnitzii, which is known for its abundance in the healthy human microbiota and depletion in various intestinal disorders, including CRC, was associated with the methylation of PPFIA2, NR3C1, and EXO1." (PMID 38840170, 2024).
EXO1 also shares sentences with these, for which no sentence is quoted: Lynch syndrome (3 papers); adenocarcinoma (2); ductal carcinoma in situ (2); head and neck squamous cell carcinoma (2); neuroblastoma (2); oral cancer (2); sarcoma (2); sterility (2); triple-negative breast carcinoma (2); acute myeloid leukemia (1); Alzheimer disease (1); anemia (1); Autoimmunity (1); breast adenocarcinoma (1); Cognitive impairment (1); colorectal polyps (1); deficiency (1); endometrial cancer (1); fungal infection (1); hereditary cancer (1); Insulin resistance (1); lung squamous cell carcinoma (1); metastasis (1); metastatic prostate carcinoma (1); migraine (1); myelogenous leukaemia (1); non-small cell lung carcinoma (1); Obesity (1); Pan (1); pancreas (1).
A further 7 diseases each share a sentence with EXO1 in 1 paper.